MMP7 (matrix metallopeptidase 7)
Diseases named in the same sentence as MMP7 in open-access papers (continued):
Sharing a sentence is not in itself a finding about the gene and the disease.
cancer (continued). "FasL can be cleaved by metalloproteinases such as MMP-7, ADAM10, and MMP-3 in various cell types and under various conditions, such as osteoblast apoptosis, T-cell activation, and the acquisition of chemoresistance by cancer cells." (PMID 32053892, 2020). "None of the 5 tested polymorphisms showed a correlation with cancer risk in studied groups, although for MMP-2, MMP-7 and MT2A non-significant differences in genotypes frequencies among cases and controls were observed." (PMID 32765800, 2020). "Hence, to explore the effect of MMP7 on CAL7 and SCC9 cell migratory behavior, the Transwell assay (in which the carcinoma cells in the chamber migrate across the membrane to the opposite side because of the lack of FBS) was performed." (PMID 31937294, 2020). "MMP-7 and MMP-9 may be involved in the blockage of cancer angiogenesis by cleaving plasminogen and generating angiostatin molecules." (PMID 31921634, 2019). "MMP3, MMP7, MMP12 and MMP14) are significantly up-regulated in at least 10 cancer types." (PMID 31200666, 2019). "These were chosen based on their gene expression patterns in cancer according to the literature survey: KRT5 and MMP7 for increased gene expression in cancer, KCNH2 for ambiguous expression in cancer, and CYP21A2 for unknown expression in BC." (PMID 31569550, 2019). "Interestingly, MMP2, MMP7, MMP23B, MMP27 and MMP28) are significantly down-regulated in seven to nine cancer types." (PMID 31200666, 2019). "However, it appears that MMPs are important enzymes involved in local attack and metastatic PTC cancer, being reported in several studies related to different members of the MMP family, including MMP-1, MMP-2, MMP-7, MMP-9, MMP-10, MMP-13, MMP-14 and MMP-15." (PMID 30509240, 2018). "We found that the expression levels of the genes in the Wnt/β-catenin signaling pathway, including APC, β-catenin, TCF7L1, TCF7L2, LEF1, MMP7, C-myc, C-jun, CYCLIND1 and GSK-3β, were remarkably higher in cancer than non-cancer tissues in the p.1125Val>Ala mutant FAP family members." (PMID 29050326, 2017). "Gene expression analyses revealed that cancer stem cell markers MMP7 and ALDH1A3 were neither transcribed before nor after PDT in CAL-33 cells." (PMID 27716314, 2016). "MMP7 and MMP9 are expressed in cancer cells that invade nervous tissue." (PMID 26576639, 2015). "All proteins (Wnt4, MMP7, CD1 and c-MYC) tested were expressed in penile tissue (141 penile tissue cores from 101 unique tissue samples of which 18 were normal/cancer adjacent and 83 were malignant samples)." (PMID 25901368, 2015). "MMP-7 (matrilysin) exhibits high activity against collagen IV, a major component of bone marrow stroma (BMS) and other basement membranes and has been found previously in carcinoma cells of many cancers including prostate and their metastases." (PMID 11953862, 2002). "Although a number of pathways related to cancer, such as PI3k-Akt, HIF-1 among others, were all enriched among the top DEGs in these datasets, Wnt signalling was significantly enriched compared to other pathways, with genes such as SFRP4, MMP7, among others, being involved." (PMID 37466730, 2023). "However, the downregulation of ADAMTS2, ADAMTS14, MMP11, and MMP7, metalloproteases that help in cancer cell invasiveness by dissolving the ECM components, could prevent cancer invasive potential." (PMID 37834191, 2023). "In addition, activated platelets secrete lysophosphatidic acid, which upregulates matrix metalloproteinase 2 (MMP2), MMP7, and MMP9 activities in cancer cells, then promote cancer progression by facilitating the detachment of cancer cells from their primary site and into the circulation." (PMID 37153586, 2023). "Sequencing results showed that Wnt7a, Wnt7b, Fzd2, Mmp7 and Ccnd2 in the Wnt signaling pathway were downregulated after PRDX6 knockout, suggesting that this signaling pathway may be involved in the regulation of PRDX6's cancer-promoting effect." (PMID 36209344, 2022).
cancer (continued). "Mmp7+ Paneth-like cancer cells were present in Tyk2Δ/Δ, but they did not express Ido1." (PMID 36185806, 2022). "MMP7 was among the few genes expressed exclusively in cancer, but not in the normal epithelium." (PMID 34409732, 2021). "As our IHC and in silico analyses uniformly suggested the importance of stromal cells in the modulation of MMP-7 expression, we speculate that in vitro analyses with cancer monoculture may not be fully representative regarding the functional spectrum of MMP-7." (PMID 33396213, 2020). "Regarding pancreatic juice, MMP-7 levels were higher in carcinoma, but not significantly so." (PMID 32751899, 2020). "In our experiments, we confirmed that the protein expression of VEGF, MMP-2, MMP-7 and MMP-9 in mouse GC tissue was significantly increased after activation of ADRB signalling under the condition of chronic stress; thus, these proteins play a role in promoting cancer and metastasis." (PMID 31624248, 2019). "Additionally, cross-talk between MMP-7 and MMP-9 leads to the cleavage of insulin-like growth factor-binding protein 2 (IGFBP-2), an angiogenic activator in major aggressive cancers via the transcriptional regulation of the VEGF gene, showing adverse effects in cancer angiogenesis in some tissues." (PMID 31921634, 2019). "Consistently, we found that glutamine deprivation could induce a decrease of MMP7 (data not shown), a marker of cancer metastasis and also a downstream target of β-catenin." (PMID 28245869, 2017). "Therefore, the increased expression levels of cell cycle functional proteins MMP7, C-myc, C-jun and CYCLIND1 in the Wnt/β-catenin signaling pathway that we observed here in the cancer tissue may have contributions also from other genes or factors." (PMID 29050326, 2017). "MMP-7 and TIMP-1 may play a role in the pathogenesis of cancer disease." (PMID 28662671, 2017). "MMP-7 and MMP-9 are members of the matrix metalloproteinases (MMPs) family, which are extracellular proteinases that regulate basic cellular processes including survival, migration and morpho-genesis and degradation extracellular matrix during the cancer metastatic process." (PMID 26840018, 2016). "MMP-7 and MMP-9 are members of the matrix metalloproteinases (MMPs) family, which are located in extracellular and control basic cellular processes, such as morpho-genesis, migration and survival, and they can degrade extracellular matrix during the cancer metastatic process." (PMID 27166267, 2016). "Because MMP-2 and MMP-9, as well as MMP-7, are known to be the downstream targets of β-catenin, significant inhibition in the level of β-catenin by embelin may inhibit MMP-2 activity and cancer cell migration." (PMID 26252009, 2015). "Conversely, the release of DNA in cancer patients, due mainly to apoptosis and necrosis processes, may explain the lack of correlation with MMP-7, which is minimally involved in these types of processes." (PMID 24336111, 2013). "MMP7, however, with a p-value of 0.54, does not exhibit a statistically significant correlation, suggesting its expression may not be a reliable indicator of survival in these cancers." (PMID 38707175, 2024). "Both MMP-3 and MMP-7 in cancer cells may or may not determine tumor resistance to apoptosis." (PMID 38203373, 2023). "Genes upregulated by >1.5‐fold in cancer tissues rather than in normal intestinal mucosae include Wnt signaling‐related genes such as Fzd1 (fold change [FC], 5.6), Myc (FC, 2.6), Ccnd1 (FC, 1.6), Mmp2 (FC, 10.4), Mmp7 (FC, 16.0), Mmp8 (FC, 12.9), Mmp12 (FC, 52.2), and Spp1 (FC, 149.3)." (PMID 35274815, 2022). "Moreover, soluble E-cadherin in serum serves as cancer prognostic marker and the soluble fragment in urine corresponds to the 80 kDa ectodermal fragment of the protein, which can be cleaved by several proteases including plasmin, MMP3, MMP7, ADAM10, and ADAM-15." (PMID 32121033, 2020). "Although it is not as regularlyexpressed in healthy kidneys, MMP7 is upregulated in CKD and cancers." (PMID 39398183, 2024).
cancer (continued). "Of note, MMP7 also cleaves the receptor of CD95L, CD95 and by doing so, promotes its ability to implement non-apoptotic signaling pathways in cancer cells." (PMID 36544756, 2022). "We found that 76.3% and 62.2% of carcinomas had negative expression of PTEN and positive expression of MMP-7 expression, respectively." (PMID 28333147, 2017). "However, the role of circulating levels of MMP-7 and MMP-26 in cancer progression and development has still not been elucidated." (PMID 33916127, 2021). "In breast cancer, it has been shown that the noncanonical Wnt 5a signaling activation in TAM promoted cancer cell migration through phosphorylation of JNK, followed by an increase in transcription of AP-1/c-Jun and matrix metalloprotease, MMP7, ultimately leads to the secretion of TNF." (PMID 32283687, 2020). "However, when comparing patients with benign pathologies and cancer, differences in MMP-1 and MMP-7 resulted not significant (Mann-Whitney U test, P = 0.448 for MMP-1 and P = 0.090 for MMP-7)." (PMID 28117344, 2017). "The expression levels of cell cycle proteins MMP7, C-myc, C-jun, CYCLIND1 and β-catenin degradation protein GSK-3β in the Wnt/β-catenin signaling pathway were higher in cancer than in non-cancer tissues in all the wild type and the homozygous and heterozygous variations of the patients." (PMID 29050326, 2017).
infection (50 papers, 2009 to 2026). The state of being infected such as from the introduction of a foreign agent such as serum, vaccine, antigenic substance or organism. "avium infection that recapitulates features of CD-associated inflammation both with high-resolution imaging and transcriptomics and identifies Mmp7 as a potential molecular link between infection and CD-like pathology." (PMID 41688878, 2026). "Suwen Ou showed that infection with F. nucleatum enhances CRC cell migration by increasing MMP7 expression through the MAPK (JNK)‐AP1 pathway." (PMID 40070022, 2025). "In contrast to Lyz1, mature SAL clusters showed elevated abundances of Reg3g, Mptx2, and Mmp7, genes known to enrich in Paneth cells, especially during infection." (PMID 38823640, 2024). "In our immunofluorescence analysis, we observed a significant elevation in MMP-7 levels of acutely infected mice, contrasting the reduced levels observed in those mice long-term post-infection." (PMID 37626956, 2023). "Here, our works initially found that MMP7 played a vital role in F. nucleatum-infection promoted CRC cell migration." (PMID 37814323, 2023). "The results revealed that expression of matrix metalloprotein 7 (mmp7) was upregulated in infection-III and -IV in contrast to infection-II after 12 hpi." (PMID 34585958, 2021). "Our study target, MMP-7, is found constitutively in the IECs and associated with tissue remodeling and the IEC response to infection." (PMID 34769248, 2021). "Nonetheless, we noticed an increased expression of cell migratory genes mmp3 and mmp7 in infection-III and -IV in comparison to infection-I and -II." (PMID 34585958, 2021). "Lentiviral infection with dn-Erk significantly decreased MMP-7 expression compared with the untransfected control." (PMID 34769248, 2021). "Infection with Mycobacterium tuberculosis causes cellular injury by increasing the production of MMP-10, MMP-1, and MMP-7 in macrophages." (PMID 34944659, 2021). "The overexpression of mmp3 and mmp7 in infection models indicated a probable role of I10 and EBV in gankyrin-mediated aggressiveness of GC through the upregulation of such kinds of cell migratory genes." (PMID 34585958, 2021). "Our results showed that MMP-7 was more frequently expressed in male than in female patients with GC, which may be associated with males mounting a greater and often more damaging inflammatory response to infection compared to females and with the protective effects of female sex hormones." (PMID 33005257, 2020). "Our results show that the absence of the brain during development leads to defects in the response against infection, specifically the accumulation of mmp7+ cells in the ventral niche reveals defects in macrophage migration." (PMID 32047653, 2020). "In saline-pretreated mice, SL1344 infection resulted in a significant induction of Reg3γ (3.8-fold), Defa1 (6-fold), MMP-7 (2.6-fold), and Ang-4 (8.6-fold) expression." (PMID 29616040, 2018). "Infection of paraoxon-pretreated mice also led to a significant enhancement in the expression of Defa1 (2.3-fold), MMP-7 (1.6-fold), and Ang-4 (4.3-fold) antimicrobial proteins, but not Reg3γ which was already upregulated by paraoxon treatment." (PMID 29616040, 2018). "Our findings indicate that following oral infection with Salmonella, saline-pretreated mice strongly upregulated the expression of RegIIIγ, Defa1, MMP-7, and Ang-4." (PMID 29616040, 2018). "We obtained a nearly identical 1.6-fold increase in infection of wild type compared to Mmp7-/- enteroids." (PMID 28622386, 2017). "Wild type and Mmp7-/- mice were infected orally with 1x106 iu/mouse of MAdV-2, and fecal shedding was monitored at 2, 4, and 7 d post-infection." (PMID 28622386, 2017). "Quantification of mmp7-expressing cells in whole populations of embryos amputated and/or infected showed that, at stage 28 (2 h after amputation), infection resulted in a decreased amount of mmp7-expressing myeloid cells." (PMID 29302351, 2017).
infection (continued). "The MMP-7 response to infection and the decrease in ASC and NLRP-3 levels were confirmed by Western blot analysis." (PMID 27732661, 2016). "ASC was shown to pull down NLRP-3 in nuclear extracts of uninfected cells but after infection, a reduction in ASC/NLRP-3 interaction was detected suggesting that a loss of ASC/NLRP-3 interaction in the nuclear compartment accompanies MMP7 activation." (PMID 27732661, 2016). "After infection of human bladder epithelial cells, with CY-17 and CY-92, we detected a significant increase in MMP-7 staining (confocal microscopy)." (PMID 27732661, 2016). "Rather, we observed decreased viral loads in multiple organs of wild type mice compared to Mmp7-/- mice only at late times post-infection (p.i.)that were coincident with the elaboration of a robust NAb response in wild type but not Mmp7-/- mice." (PMID 26933888, 2016). "When immune response was determined in the cecum, the infection of newly hatched chickens with S. Enteritidis led to a significantly increased expression of all tested genes with matrix metalloproteinase 7 (MMP7) being upregulated nearly 1000×." (PMID 26380970, 2015). "It includes genes related to collagen production and organization (COL6A3, COL6A2, COL6A1, etc.), or matrix metalloproteinases (MMP) involved in extracellular matrix remodelling (MMP7, MMP23B), and previously implicated in infection response." (PMID 26331304, 2015). "MMP7 activity results in tissue relaxation enabling penetration of leukocytes to the site of infection." (PMID 25475706, 2014). "Only MMP7 was significantly induced in the cecum 4 days after the infection with the Salmonella Enteritidis SPI1 mutant." (PMID 23687968, 2013). "The most inducible gene was that coding for MMP7, exhibiting a 5952 fold induction 9 days post-infection." (PMID 23687968, 2013). "Susceptible WT (FvB, BALB/c and C57BL/6) mice and mutant mice with altered intestinal innate immunity, specifically CRAMP KO and MMP7 KO mice, were infected with S. Typhimurium to determine the potential role of these CAMPs during infection." (PMID 23166721, 2012). "Between 20 and 28 h post-infection, wild type mice shed significantly more virus than Mmp7-/- mice." (PMID 28622386, 2017). "The increase in mmp7-positive cells (and, therefore, migratory immune cells) shown in embryos depolarized with barium chloride could explain the observed increase in infection-resistance." (PMID 29302351, 2017). "Furthermore, increased fecal shedding was observed from wild type mice compared to Mmp7-/- mice after oral infection with MAdV-2." (PMID 28622386, 2017). "Although there may be some contribution of direct α-defensin antiviral activity to modulating infection, the delayed NAb response appears to be primarily responsible for the survival difference between the wild type and Mmp7-/- mice." (PMID 26933888, 2016). "Quantitative real-time RT-PCR (qRT-PCR) analysis was used to measure the mRNA expression levels of β-catenin, cyclin D1, Dvl, LRP5, or matrix metalloproteinase-7 (MMP7) after infection with RVFV MP12 or RVFV MP12-GFP (MOI of 1) or treatment with Wnt3A in A549 cells." (PMID 27226375, 2016). "However, the fold induction (35 fold) after infection with the SPI1 mutant was 45× lower when compared with the MMP7 induction in the cecum of chickens infected with the wild-type Salmonella Enteritidis (1578 fold)." (PMID 23687968, 2013). "However, even in the case of MMP7, its induction 4 days post-infection with the SPI1 mutant (35 fold) was significantly lower than after infection with wild-type Salmonella Enteritidis (1578 fold)." (PMID 23687968, 2013). "Reactive astrocytes produce a variety of factors in response to injury and infection, so we examined whether astrocytes expressed MMP-7 during EAE by co-immunostaining for glial fibrillary acidic protein (GFAP)." (PMID 19267908, 2009). "Furthermore, the expression level of MMP7 rose along with the MOI or the time after infection." (PMID 37814323, 2023).